INS (insulin)
Diseases named in the same sentence as INS in open-access papers (continued):
Sharing a sentence is not in itself a finding about the gene and the disease.
Hypoglycemia (continued). "Compensation with diet and insulin adjustments in order to avoid exercise-induced hypoglycaemia could explain the absence of effect on glucose control." (PMID 34427840, 2022). "Although there is no overall consensus on indications for insulin pump therapy, it is widely accepted that those with frequent, severe hypoglycemia and/or hypoglycemia unawareness may derive particular benefit." (PMID 35757419, 2022). "There are two main approaches to insulin-glucagon systems: the first utilizes small boluses to prevent hypoglycemia without a concomitant increase in insulin delivery, while the second uses intermittent glucagon doses to allow more aggressive insulin delivery to target lower glucose levels." (PMID 35733769, 2022). "However, in rare cases, hypoglycemia can be found together with low levels of insulin in non-diabetic patients, in the so-called hypoinsulinemic hypoglycemia." (PMID 35282439, 2022). "Strengths of this study include that although the use of IV insulin in patients with MRS has been previously reported, few had data on glycemic control, and none had described the importance of hypoglycemia treatment and the use of CSII with a predictive hypoglycemia minimizer." (PMID 35813646, 2022). "PMM2-HI is diagnosed in the same manner as other types of CHI, based on the child’s presentation of non-ketotic hypoglycemia, requiring large amounts of glucose infusion to control hypoglycemic episodes, and overproduction of insulin which is incompatible with hypoglycemia." (PMID 36726472, 2022). "However, it has been previously shown that hepatic insulin extraction in dogs is not affected by tolbutamide-induced hypoglycemia." (PMID 35887007, 2022). "The hypoglycemia‐activated glucagon booster release from the GRS glucagon MN patch was validated on two groups of diabetic mice: one exhibiting hyperglycemic PGLs (untreated) and one undergoing hypoglycemic PGLs (treated with 15 h‐fasting and a subcutaneous injection of 75 μg kg−1 insulin)." (PMID 35957510, 2022). "No participant without insulin therapy presented hypoglycemia." (PMID 36187123, 2022). "However, in studies investigating the potential benefit of adding glucagon to artificial pancreas devices, glucagon has been administered to prevent hypoglycaemia and not with insulin infusions or in relation to meals." (PMID 36213069, 2022). "Thus, while her insulin requirements were not high, she had poor diabetic control (HbA1c > 73 mmol/mol) but also suffered episodes of hypoglycaemia and hypo‐unawareness." (PMID 35281666, 2022). "When high fat diet (HFD) without sufficient glucose is consumed, hypoglycemia may occur, provided that glucagon does not elevate while insulin secretion increases." (PMID 36246919, 2022). "However, this represents at least a significant amount of ketosis, which does not support insulin-mediated hypoglycemia." (PMID 35897673, 2022). "However, many patients remain in suboptimal or non-staggered treatments, especially with insulin, out of fear of hypoglycemia and weight gain." (PMID 35573995, 2022). "Thus, in patients with stable T2D and cardiovascular disease, Px increases anti-aggregatory responsiveness to NO, but is not an insulin sensitizer, and does not induce hypoglycaemia." (PMID 36289640, 2022). "Moreover, individuals with long-duration T1D are complicated with autonomic neuropathy when they have markedly reduced or absent responses of NPY to insulin-induced hypoglycemia." (PMID 35627254, 2022). "Although significant reductions in mean HbA1c were observed regardless of treatment (≤1 medication vs. ≥2 medications) patients treated with ≤1 medication (insulin or noninsulin) showed the greatest improvements in %TIR and %TAR without increasing hypoglycemia risk." (PMID 34524013, 2022). "However, we found that levels of insulin did not increase until a late stage, when hypoglycemia was already established." (PMID 36548717, 2022).
Hypoglycemia (continued). "Some authors also consider the ratio of insulin to C-peptide (I:C) to be a useful measure to distinguish between exogenous and biological hypoglycaemia as C-peptide is only formed with release of endogenous insulin, and should not be > 1 in a healthy individual." (PMID 35943711, 2022). "Thus, Agpat5 in AgRP neurons plays a role in hypoglycemia sensing but not in whole body insulin sensitivity." (PMID 36180454, 2022). "This study suggests vasodilatory beta‐blockers such as carvedilol may reduce the incidence of hypoglycaemia in diabetic patients who are not on basal insulin therapy." (PMID 33855225, 2021). "In addition, in the absence of glucose, such as insulin-induced hypoglycemia, microglia utilize glutamine as an alternative fuel to support their immunological functions." (PMID 34795562, 2021). "Female mice lacking glutamate receptors in the VMH have impaired insulin sensitivity and glucose regulation but without any deficit in responding to a hypoglycemia challenge suggesting that glutamate input is not the primary driver of GI neuron activation within the VMH." (PMID 33746780, 2021). "The probable reason for less incidence of hypoglycaemia with Hydroxychloroquine may because of its actions at peripheral levels i.e. insulin degradation in the target cells and thus facilitate insulin recycling, unlike any secretagogue." (PMID 32594451, 2021). "The lack of access to food is especially concerning for people who are using insulin, as they may use less than the prescribed amount of insulin for fear of developing hypoglycemia if they are not able to predict mealtimes reliably." (PMID 34243783, 2021). "Therefore, we started him on an insulin pump and continuous glucose monitoring showed flatter curve of the blood glucose and no hypoglycemia attack afterward." (PMID 33879153, 2021). "Insulin doses were titrated and no patient experienced repeated hypoglycemia." (PMID 33478575, 2021). "In regard to TPAIT, evaluation of endogenous insulin production is vital in order to predict future islet yield which reasonably corelate with insulin production post-operatively as well as good glycemic control without problems of hypoglycemia." (PMID 34068902, 2021). "However, blood glucose normalized 8 h after insulin administration, implying that reduced mimecan expression is not induced by hypoglycemia state." (PMID 33971622, 2021). "Human clinical trials concluded that treatment with intravenous insulin to maintain normoglycemia after ischemic stroke did not provide any benefit in terms of functional outcomes, and exposed, more frequently, patients to acute hypoglycemia." (PMID 33925459, 2021). "Although the group of concomitant insulin users also reported no change in hypoglycemia occurrence, this could have been mitigated by the on average 10–20% reduction in total daily insulin dosage." (PMID 34305810, 2021). "Metformin has been reported to work by minimizing the absorption of intestinal glucose, enhancing peripheral glucose uptake, reducing the amount of fasting plasma insulin, and rising insulin sensitivity, resulting in a drop in blood glucose levels without inducing hypoglycemia." (PMID 34812979, 2021). "The increased release of AVP in response to hypoglycemia appears to be independent of insulin." (PMID 34867449, 2021). "However, it should be pointed out that all T1DM subjects modified insulin dose before the bout of exercise and, therefore, none of them experienced symptoms of hypoglycemia." (PMID 33633280, 2021). "However, a large percentage of patients with T1DM people present a sedentary behavior because of the fear of a post-exercise hypoglycemia event, lack of time, lack of motivation and the complicated management of exercise, glycemic and insulin dose interaction." (PMID 34886337, 2021).
Hypoglycemia (continued). "Our study indicated that in people with T2DM and compensated cirrhosis, insulin users showed higher risks of all-cause mortality, cardiovascular events, HCC, decompensated cirrhosis, hepatic failure, and hypoglycemia than insulin nonusers, even after excluding persons with hypoglycemia." (PMID 34118892, 2021). "Moreover, some studies have reported that risperidone induces hypoglycemia by increasing insulin secretion in nondiabetic patients with schizophrenia." (PMID 33401717, 2021). "Furthermore, after 3 days of insulin using, 96.3% of patients did not have hypoglycemia, while 3.4% of patients had 1–3 times of hypoglycemia, 3% had more than 3 times of hypoglycemia." (PMID 33483468, 2021). "In other words, the principle of DPP-4 is the increase in insulin secretion following food intake and the period of insulin secretion time can be improved, and blood glucose levels can be additionally improved by suppressing glucagon secretion without inducing hypoglycemia." (PMID 34489627, 2021). "Some protocols propose that if serum cortisol is drawn at 08:00 and the level is below 3–5 μg/dL (83–138 nmol/L), it is strongly suggestive of AI and indicates that other dynamic tests, e.g., an ACTH stimulation test or insulin-induced hypoglycemia, are not necessary." (PMID 33801854, 2021). "Diagnosis may also be complicated by insulin levels not always being elevated in hypoglycaemia, pointing to the impact of liver glucose disposal, which is also determined by GK activity, on glucose homeostasis." (PMID 34532767, 2021). "In Tandem3, a phase 3 double-blind clinical trial, the authors concluded that the proportion of patients with T1DM on insulin and who received sotagliflozin accomplished a HbA1c level of less than 7.0% (without severe hypoglycemia or diabetic ketoacidosis (DKA)) was larger than the placebo group." (PMID 34884494, 2021). "Thus, severing the common hepatic artery sympathetic nerves was without effect on ketogenesis during insulin‐induced hypoglycemia." (PMID 33769710, 2021). "Closed-loop could not prevent exercise-related hypoglycemia, and so, fast-acting carbohydrates were still required especially for postmeal exercise when prandial insulin is still active." (PMID 33512267, 2021). "Hypoglycemia may also occur during insulin dose adjustment, with a negative impact on cardiovascular mortality." (PMID 33801468, 2021). "CGM devices should be considered for patients with T1D and T2D who are on intensive insulin therapy to improve HbA1c levels and reduce hypoglycemia (Grade B), early reports suggest that even patients not taking insulin may benefit from CGM (Grade D)." (PMID 33534631, 2021). "In addition, studies also have shown that SGLT2 inhibitors, in combination with complex insulin regimens, had lower insulin dose requirements and lowered body mass without incurring hypoglycemia." (PMID 34281221, 2021). "Thus, prolonged (>45 min) or high-volume exercise can result in hypoglycemia in insulin treated women with GDM if adjustments in insulin dose are not made." (PMID 33870263, 2021). "While suppression of C-peptide may be expected in response to exogenous insulin administration, the presence of substantial C-peptide immunoreactivity in the context of recurrent hypoglycemia in IAS has not been explained." (PMID 34051096, 2021). "However, calorie restricted mice were not able to recover from the hypoglycemia induced by the insulin injection by the end of the insulin tolerance test (Time 120′ on the graph)." (PMID 34736458, 2021). "Glucose-lowering medications that act by increasing insulin sensitivity do not induce hypoglycemia." (PMID 34832978, 2021). "Furthermore, as neonatal hyperinsulinemia is the major reason for neonatal hypoglycaemia in offspring born to mothers with GDM, the neonatal plasma insulin level may better reflect the in utero environment compared to PG." (PMID 34267729, 2021).
Hypoglycemia (continued). "However, the metabolic fate of the glucose following TO-induced insulin secretion and consequent hypoglycaemia is not clear." (PMID 33997754, 2021). "Thus, in insulin‐sensitive tissues (i.e., skeletal muscle and adipose tissue), TXNIP seems to decrease the number of GLUT4 transporters on the cell surface and reduce the glucose uptake in order to prevent hypoglycemia under fasting conditions." (PMID 32476292, 2020). "However, the highest glucose concentration in the LG group was 156 mg/dl and none of the patients in either group required intravenous insulin or experienced hypoglycemia (< 70 mg/dl)." (PMID 32505171, 2020). "Therefore, the dose of insulin and/or insulin secretagogues may need to be reduced when combined with an SGLT2 inhibitor, to avoid hypoglycemia." (PMID 32403420, 2020). "Pharmacologic administration of FGF21 imparts resistance to high-fat-diet–induced weight gain, improves glucose tolerance and hepatic and peripheral insulin sensitivity (without triggering hypoglycemia), and normalizes hyperinsulinemia and hypertriglyceridemia." (PMID 33210059, 2020). "In conclusion, our study confirmed that the proposed calculation method for an optimized insulin dosage in ITT led to a high rate of successful induction of adequate hypoglycemia with a single insulin dose without elevating the incidence of serious adverse events." (PMID 32328036, 2020). "We compared baseline parameters between patients with moderate hypoglycemia and patients with only mild hypoglycemia and found that those who experienced moderate hypoglycemic episodes had higher baseline levels of HbA1c, FPG, PPG, TC, LDL-C, hsCRP, and initial insulin dosage." (PMID 32149152, 2020). "Insulin therapy, insulin secretagogues, skipping a meal, doing physical exercise without taking food, a history of severe hypoglycemia, alcoholic beverages, renal insufficiency, coronary artery disease, and infections are the most common reasons for the recurrent episodes of hypoglycemia." (PMID 32822414, 2020). "The percentage of participant on secretagogues was comparable among the groups of participant with or without verified hypoglycemia; i.e. half of the participants in the hypoglycemia group with a cut-off value of < 3.0 mmol/L were not receiving insulin secretagogue therapy at all." (PMID 32151247, 2020). "Moreover, some of the participants with self reported hypoglycemia were not treated with insulin secretagogue." (PMID 32151247, 2020). "BBE ingestion improved insulin sensitivity and hypoglycemia by upregulating AMPK, which upregulated GLUT4, PPAR-α, ACOX, and carnitine palmitoyltransferase-1 and ACPT-1A, which is synonymous to the suppression of glucose production and increased insulin sensitivity." (PMID 32825710, 2020). "This is represented as a greater mean latency to reach the minimum insulin-induced hypoglycemia in exposed F1 groups, 72.5 min (0.1 mg/kg) and 70 min (0.4 mg/kg), relative to VEH/CON, i.e., 37.5 min, possibly indicating delayed glucose clearance/utilization in response to insulin." (PMID 33093533, 2020). "In addition, active uncontrolled oversecretion of insulin by insulinoma is not regulated by the feedback of blood glucose, and this is the primary feature of insulinoma and the basis of hypoglycemia." (PMID 32124259, 2020). "In 1962, Pereda and collaborators showed that insulin infusion in the absence of hypoglycemia promoted an increase in arterial blood pressure and SNS activity in anesthetized dogs, and this sympatho-excitation was higher when insulin was administered into the carotid artery than systemically." (PMID 32698380, 2020). "In the present study, we demonstrated that the proposed personalized calculation method for an optimized insulin dosage in ITT led to a high rate of successful induction of adequate hypoglycemia with a single dose of insulin, without elevating the incidence of serious adverse events." (PMID 32328036, 2020).
Hypoglycemia (continued). "But maintaining blood glucose levels into near-normoglycemia is not a trivial task, and if insulin is overdosed, BG may fall to dangerously low levels (hypoglycemia), which can lead to serious hazards, such as diabetic coma or even death." (PMID 32399164, 2020). "The multivariate logistic regression model showed that male gender, daily insulin dosing, duration of the therapy, coefficient of variation, and standard deviation of glucose measures calculated by CGM were the most related factors to the presence of clinically significant hypoglycemia." (PMID 32832557, 2020). "Therefore, it is important to achieve adequate hypoglycemia without adverse events by choosing an accurate insulin dose for an ITT." (PMID 32328036, 2020). "Even when glucagon secretion could not be properly stimulated by insulin-induced hypoglycemia in CP related DM patients, preserved catecholamine response to hypoglycemia largely preserved glucose counterregulation." (PMID 33250773, 2020). "Other nutrients, such as fatty acids and amino acids, are not bona fide stimuli for the induction of insulin secretion, probably because they are recruited in the post-prandial state that should avoid elevation of circulating insulin in order to prevent hypoglycemia." (PMID 32492936, 2020). "Indeed, since it is not possible to inject insulin in healthy patients (since they can die with hypoglycemia), insulin interference in healthy lungs remains still unraveled." (PMID 32117245, 2020). "Unfortunately, the introduction of new technologies such as shorter and longer acting insulin analogs, insulin pumps, and continuous glucose monitors (CGMs) have not eliminated the occurrence of hypoglycemia events in young children or reduced caregiver fear of hypoglycemia." (PMID 32808936, 2020). "Common reasons for insulin discontinuation included the cost of medication and/or test strips (43.1%), impact of treatment on social life (36.2%), lack of support (25.9%) and fear of hypoglycaemia (25.9%)." (PMID 32569176, 2020). "The guidelines recommend less stringent targets in patients who are unable to communicate their symptoms or who have hypoglycemia unawareness, recurrent severe hypoglycemia, lack of access to insulin analogs and advanced insulin delivery technology, or inability to regularly monitor BG levels." (PMID 32256447, 2020). "This trial also reported a similar overall risk of hypoglycaemia between the two insulins and a lower rate of hypoglycaemia in the titration period with glargine U300 vs insulin degludec, while no evaluation of severe hypoglycaemia was conducted as only one event was recorded during the trial." (PMID 31984443, 2020). "A confirmed case of V8-associated hypoglycemia was defined as the development of severe hypoglycemia within 48 hours of consuming an over-the-counter male enhancement supplement in a man with no history of use of insulin or other medication used to control blood glucose." (PMID 32555139, 2020). "However, there was a significant interaction by basal insulin use such that hypoglycemia was only increased in patients who were not using basal insulin." (PMID 31775749, 2019). "Patients with IAS usually complain of hypoglycemia without any previous insulin received." (PMID 31883520, 2019). "Although a similar subset of medullary neurons is activated after either 2-DG or insulin injections, the physiological mechanisms underlying HAAF must be determined with models of insulin-induced hypoglycemia, rather than glucoprivation, to maintain biological relevance." (PMID 31013147, 2019). "Thus, more pronounced actions of GCs in female mice might overrule the inhibitory effect of insulin on EGP or, alternatively, the FBG levels of corticosterone-treated mice were at their lowest limit, which requires EGP to prevent symptomatic hypoglycemia." (PMID 31265057, 2019).